BCR (BCR activator of RhoGEF and GTPase)
Diseases named in the same sentence as BCR in open-access papers (continued):
Sharing a sentence is not in itself a finding about the gene and the disease.
chronic myeloid leukemia (continued). "It was possible to transfer the hybrid BCR/ABL gene, involved in the pathogenesis of chronic myeloid leukemia (CML), to neutrophils from EVs derived from K562 in an in vitro model." (PMID 33227947, 2020). "Another example involves chronic myeloid leukemia (CML) cells, which undergo a genetic alteration known as BCR-ABL." (PMID 32916938, 2020). "In chronic myeloid leukaemia (CML), the level of cells with the BCR‐ABL rearrangement is widely used to characterize the disease progression, and decreases after imatinib treatment." (PMID 30873683, 2019). "Chronic myelogenous leukemia is a HSC‐driven hematological malignancy that is characterized by HSC translocation, leading to the expression of the active tyrosine kinase BCR/ABL." (PMID 31373443, 2019). "Chronic myelogenous leukemia (CML) is a common hematological malignancy in adults and has the molecular characteristic of BCR-ABL fusion proteins, which exhibit abnormal kinase activity." (PMID 31223481, 2019). "BCR-ABL fusion kinase (BCR: Breakpoint cluster region; ABL: Abelson murine leukemia viral oncogene homolog 1) is frequently found in chronic myeloid leukemia and some cases of acute lymphoblastic leukemia." (PMID 31877888, 2019). "BCR-ABL harbours a constitutively active form of the ABL TK and is present in more than 90% of chronic myeloid leukemia (CML) patients." (PMID 29455660, 2018). "For instance, nilotinib belongs to therapeutic agents used in the clinic that inhibit the tyrosine kinase activity of the fusion oncogene BCR‐ABL and are highly effective against Chronic Myeloid Leukaemia (CML)." (PMID 29438985, 2018). "Imatinib, a tyrosine kinase inhibitor (TKI), was known to inhibit c-kit as well as BCR-ABL fusion protein, the target of chronic myeloid leukemia (CML)." (PMID 29510588, 2018). "This study was done to determine the frequency of BCR-ABL fusion genes and laboratory findings of patients with chronic myeloid leukemia in northeast Iran." (PMID 29387322, 2018). "Imatinib revolutionized the treatment of chronic myeloid leukemia (CML) in 2001, a disease in which the BCR-ABL fusion occurs." (PMID 29455659, 2018). "Dasatinib is a second generation BCR/Abl tyrosine kinase inhibitor (TKI) approved for first-and second-line use in patients with chronic myeloid leukemia (CML) and Philadelphia chromosome-positive acute lymphoid leukemia." (PMID 29867576, 2018). "Chronic myeloid leukemia (CML) is a form of hematopoietic stem cell disease characterized by the presence of the oncogene BCR-ABL, which is created by the fusion of BCR and ABL genes and results in a constitutively active BCR-ABL tyrosine kinase protein." (PMID 29316665, 2018). "A specific chromosomal abnormality, the Philadelphia chromosome (BCR-ABL fusion), is present in all patients with chronic myeloid leukemia (CML)." (PMID 29387322, 2018). "In chronic myelogenous leukemia (CML), the translocation of ABL within the BCR (breakpoint cluster region) gene results in the generation of the fusion gene, BCR-ABL, which encodes a constitutively activated oncogenic tyrosine kinase Bcr-Abl." (PMID 27903968, 2017). "The development of Imatinib mesylate (IM), which targets the oncogenic BCR-ABL fusion protein, has greatly improved the outcome of Chronic Myeloid Leukemia (CML) patients." (PMID 28533480, 2017). "At diagnosis, about 5% of Chronic Myeloid Leukemia (CML) patients lacks Philadelphia chromosome (Ph), despite the presence of the BCR/ABL rearrangement." (PMID 28404889, 2017). "Chronic myeloid leukaemia (CML) is just such an example, where the introduction of taking new oral medications, the tyrosine kinase BCR-ABL inhibitors (TKI), has now revolutionised the treatment." (PMID 28444623, 2017). "For example, the BCR-ABL fusion oncogene, targeted by imatinib, is a major driver of tumorigeneis in chronic myelogenous leukemia." (PMID 27793177, 2016).
chronic myeloid leukemia (continued). "Chronic myelogenous leukemia (CML) is a common hematologic malignancy, characterized by the formation of Philadelphia (Ph) chromosome and BCR-ABL fusion gene." (PMID 26942564, 2016). "For instance the well-known gene fusion in chronic myelogenous leukemia leading to an mRNA transcript that encompass the 5’ end of the BCR gene and the 3’ end of the ABL gene, producing the chRNA BCR–ABL." (PMID 27822312, 2016). "Recently, we observed that, in chronic myeloid leukemia (CML), a myeloproliferative disorder sustained by the t(9:22) translocation coding for the chimeric protein BCR-ABL, the IκB-α protein is highly expressed in the cytoplasm." (PMID 27916821, 2016). "Although, several tyrosine kinase inhibitors targeting the BCR-ABL hybrid have been developed and shown to be successful for chronic myeloid leukemia treatment, leukemia cells can become resistant to treatment." (PMID 27832139, 2016). "A convincing example is fusion gene BCR-ABL, which can be translated to an abnormal fusion protein-tyrosine kinase and drive the development of chronic myelogenous leukemia (CML)." (PMID 27506935, 2016). "Another early example of a successful single-gene assay is that of chronic myeloid leukemia (CML), in which the BCR–ABL fusion protein results from a chromosomal translocation event found in ~90% of CML patients." (PMID 27923042, 2016). "The discovery of imatinib (Gleevec), an inhibitor of tyrosine kinase activity of BCR/ABL, was a breakthrough in the treatment of chronic myeloid leukemia (CML)." (PMID 25861270, 2015). "For example, the Philadelphia Chromosome rearrangement, originally identified in chronic myelogenous leukemia (CML), is the result of a translocation between chromosomes 9 and 22 which leads to the expression of a fusion gene combining the BCR and ABL kinases." (PMID 26132974, 2015). "ABL kinase activity is perhaps best known in the context of BCR-ABL, the translocation gene product responsible for chronic myelogenous leukemia (CML) and some forms of acute lymphocytic leukemia." (PMID 26222440, 2015). "Due to its inhibition of the Abl kinase domain in the BCR-ABL fusion protein, imatinib is strikingly effective in the initial stage of chronic myeloid leukemia with more than 90% of the patients showing complete remission." (PMID 26606374, 2015). "Radotinib, developed as a BCR/ABL tyrosine kinase inhibitor (TKI), is approved for the second-line treatment of chronic myeloid leukemia (CML) in South Korea." (PMID 26065685, 2015). "The BCR/ABL1 fusion is a well-studied entity, present in all the cases of Chronic Myeloid Leukemia (CML) and approximately 20% cases of B-cell ALL." (PMID 26600955, 2015). "Altogether these results suggest BCR/ABL-OOF as an important player during cell proliferation, survival and apoptosis in chronic myeloid leukaemia." (PMID 26682280, 2015). "Chronic Myeloid Leukemia (CML) is characterized by a balanced translocation juxtaposing the Abelson (ABL) and breakpoint cluster region (BCR) genes." (PMID 26111048, 2015). "In chronic myelogenous leukemia (CML), measurement of the leukocyte alkaline phosphatase has been replaced by detection of the BCR-ABL fusion transcript—the defining criterion for this disorder." (PMID 26126599, 2015). "In chronic myeloid leukemia (CML), the dormant LSCs are largely independent on the BCR-ABL signaling and therefore cannot be eradicated by BCR-ABL tyrosine kinase inhibitors (TKIs), so that disease often reoccurs upon discontinuation of TKI treatment." (PMID 26016997, 2015). "Another well-established predictive biomarker is the oncogenic BCR-ABL gene fusion, which predicts for antitumor responses to the tyrosine kinase inhibitor imatinib in chronic myelogenous leukemia." (PMID 25277503, 2014). "Deregulated BCR-ABL oncogenic activity leads to transformation, oncogene addiction and drives disease progression in chronic myeloid leukemia (CML)." (PMID 24500518, 2014).
chronic myeloid leukemia (continued). "Increased expression of the target protein BCR/ABL, resulting from genomic oncogene amplification, was observed in chronic myelogenous leukemia (CML) cell lines that became refractory to the selective ABL tyrosine kinase inhibitor imatinib." (PMID 24885200, 2014). "One notable example is the Aurora A inhibitor MLN8237, which overcomes resistance to BCR-ABL kinase inhibitors, in chronic myeloid leukemia (CML)." (PMID 24930769, 2014). "In chronic myeloid leukemia (CML), a mutant fusion gene, Bcr-abl, codes for a constitutively active tyrosine kinase, BCR-ABL, whose inhibition by the drug imatinib mesylate (IM) dramatically reduces the cancer burden." (PMID 25099816, 2014). "The BCR-ABL fusion protein results in the Philadelphia chromosome and is present in 95% of chronic myeloid leukemia (CML) patients and 20–40% of adult acute lymphoblastic leukemia (ALL) patients." (PMID 25029499, 2014). "For example, FISH detection of BCR/ABL1 translocation, HER2 amplification, and ALK rearrangement is critical for guiding targeted therapy in chronic myeloid leukemia, breast cancer and lung adenocarcinoma, respectively." (PMID 24499728, 2014). "In light of the crucial role of the BCR-ABL tyrosine kinase in chronic myelogenous leukemia, TKIs have become the first-line therapy for most patients with chronic myelogenous leukemia." (PMID 24603487, 2014). "In chronic myelogenous leukemia (CML), the activity of the fusion BCR-ABL kinase affects adhesion signaling." (PMID 25198091, 2014). "In some instances such as chronic myelogenous leukemia (CML), the gene fusion generated as a result of the breakage–rejoining event underpinning the translocation formed a new oncogenic BCR-ABL gene fusion." (PMID 24626952, 2014). "A peripheral blood cytogenetic analysis is performed due to a high suspicion of leukemia, and the results show BCR/ABL fusion gene with a cut point in the M-BCR region, which confirms the diagnosis of chronic myeloid leukemia." (PMID 23476855, 2013). "The use of tyrosine kinase inhibitors (TKIs) that target BCR-ABL is a well-established and highly effective strategy for sustained disease control in chronic myeloid leukemia (CML)." (PMID 23801357, 2013). "Chronic myeloid leukemia (CML) arises consequently to the reciprocal translocation of chromosomes 9 and 22, t(9:22), leading to expression of the fusion gene BCR-ABL." (PMID 23365579, 2013). "Chronic myelogenous leukemia (CML) is characterized by the Philadelphia (Ph) chromosome, created by a reciprocal translocation t(9:22)(q34;q11) which forms the chimeric gene, BCR-ABL." (PMID 23420612, 2013). "Overexpression of BMI1 also enhances the leukemogenic activity of BCR/ABL, a fusion protein recurrently found in chronic myeloid leukemia (CML)." (PMID 24348510, 2013). "It has fundamentally changed the way in which chronic myeloid leukemia (CML) is treated, as BCR-ABL is a major driver of this malignancy." (PMID 23922791, 2013). "Chronic myelogenous leukemia (CML) is characterized by the Philadelphia (Ph) chromosome created by the reciprocal translocation t(9:22)(q34;q11), resulting in the chimeric gene breakpoint cluster region (BCR)-Abelson (ABL)." (PMID 23759955, 2013). "Chronic myeloid leukemia (CML) is a MPN that is characterized by the development of the Philadelphia (Ph) chromosome and the BCR-ABL fusion gene." (PMID 24385746, 2013). "Dasatinib is a BCR/ABL and src family tyrosine kinase inhibitor used in the treatment of chronic myeloid leukaemia and acute lymphoblastic leukaemia." (PMID 23816254, 2013). "Chronic myeloid leukemia (CML), the most common MPN, is characterized by a chromosomal translocation, which leads to the production of the breakpoint cluster region-abelson (BCR-ABL) fusion oncoprotein." (PMID 22007291, 2012). "Activating translocations of ABL, such as BCR-ABL, are pivotal for the development of chronic myelogenous leukemia." (PMID 22608253, 2012).
chronic myeloid leukemia (continued). "Chronic myelogenous leukemia (CML) is a clonal disease characterized by the presence of the Philadelphia chromosome and resultant BCR-Abl gene fusion with constitutively active tyrosine kinase in >90% of patients." (PMID 22216158, 2011). "The BCR-ABL fusion gene, originating in a multipotent hematopoietic stem cell, is the molecular signature of chronic myeloid leukemia (CML)." (PMID 22248740, 2011). "Chronic Myeloid Leukemia(CML) is a malignant myeloproliferative disorder originating from a pluripotent stem cell that expresses the BCR/ABL oncogene and is characterized by abnormal release of the expanded, malignant stem cell clone from the bone marrow into the circulation." (PMID 21535879, 2011). "Etiologically, chronic myelogenous leukemia (CML) is a homogeneous genetic disease, as it is triggered by the aberrant tyrosine kinase activity of the BCR-ABL translocation." (PMID 21760961, 2011). "The patient was not started on any therapy and is being followed regularly with laboratory checkup and physical examination for monitoring signs and symptoms of chronic myeloid leukemia (CML) and biological behavior of his BCR-ABL transcripts." (PMID 20182545, 2010). "Imatinib blocks many protein kinases, including fusion proteins BCR-ABL and KIT, and has been approved for the treatment of chronic myelogenous leukaemia and gastrointestinal stromal tumours." (PMID 19935796, 2010). "Imatinib is used to treat Chronic Myeloid Leukemia (CML) patients who express a constitutively active c-Abl tyrosine kinase, the BCR-ABL fusion protein." (PMID 20385023, 2010). "Dasatinib is a potent inhibitor of multiple oncogenic kinases including Src, cKIT, BCR-ABL, PDGFR, and ephrin A. Because of its ability to inhibit BCR-ABL, it was approved for treatment of chronic myeloid leukemia in 2006." (PMID 20398256, 2010). "The canonical example of a fusion gene is BCR-ABL, which results from a characteristic translocation (termed the “Philadelphia chromosome”) in many patients with chronic myelogenous leukemia (CML)." (PMID 18404202, 2008). "In the case of one these conditions, chronic myeloid leukemia (CML), the stimulus became evident with the discovery of the Philadelphia chromosome and the translocation which results in the BCR/ABL fusion gene." (PMID 17032464, 2006). "Its original target was the chimeric protein, BCR-ABL, formed as a result of the molecular juxtaposition of two genes, BCR and ABL, on a newly created Philadelphia chromosome in chronic myelogenous leukaemia (CML) patients." (PMID 15870711, 2005). "The tyrosine kinase activity of the BCR–ABL oncoprotein results in reduced apoptosis and thus prolongs survival of chronic myelogenous leukaemia cells." (PMID 11986785, 2002). "Chronic myeloid leukemia (CML) is characterized by the accumulation of myeloid precursors and mature myeloid cells and is driven by translocations between the BCR serine/threonine kinase gene and the ABL tyrosine kinase gene, resulting in a constitutively active ABL tyrosine kinase." (PMID 41498402, 2026). "Chronic myeloid leukemia (CML) is a type of blood cancer that arises due to a genetic translocation between chromosomes 9 and 22, leading to the expression of a constitutively active tyrosine kinase oncogene called BCR::ABL1." (PMID 40113750, 2025). "For instance, it strongly inhibits the growth of imatinib-resistant chronic myeloid leukemia (CML) cells, induces DNA damage in these cells, and reduces BCR-ABL transcription levels, thereby curtailing malignant proliferation and transformation without harming normal blood cells." (PMID 41041648, 2025). "Similarly, Hsp90 is crucial for the stability and function of BCR-ABL, a constantly active fusion kinase that drives chronic myeloid leukemia (CML) by activating multiple oncogenic pathways." (PMID 41226319, 2025).
chronic myeloid leukemia (continued). "Chronic myeloid leukemia (CML) is characterized by the presence of the Philadelphia chromosome (Ph), which results from a reciprocal translocation between chromosomes 9 and 22, leading to the fusion of the BCR and ABL genes." (PMID 41322795, 2025). "Chronic myeloid leukemia (CML) is a malignancy characterized by the appearance of the leukemogenic oncoprotein breakpoint cluster region::Abelson murine leukemia viral oncogene homolog 1 (BCR::ABL), which is a molecular product of the Ph1 (Philadelphia) chromosome in hematopoietic stem cells (HSCs)." (PMID 40868343, 2025). "Imatinib (Gleevec®) was the first tyrosine kinase inhibitor (TKI) designed to selectively inhibit the BCR-ABL fusion protein, which results from the oncogenic Philadelphia chromosome translocation occurring in chronic myeloid leukemia (CML) and some cases of acute lymphoblastic leukemia (ALL)." (PMID 40732226, 2025). "Chronic myeloid leukemia (CML) is a myeloproliferative neoplasm characterized by both an abnormal expansion of the granuloblastic clone and the pathognomonic presence of the Philadelphia (Ph) chromosome that generates the BCR::ABL1 oncoprotein." (PMID 41373445, 2025). "The first TKI, imatinib (a BCR–ABL TKI), was approved by the United States Food and Drug Administration (US FDA) in May 2001 for the treatment of chronic myeloid leukemia (CML)." (PMID 39184861, 2024). "Chronic myeloid leukemia (CML) is a malignant clonal disease involving hematopoietic stem cells that is characterized by myeloid cell proliferation in bone marrow and peripheral blood, and the presence of the Philadelphia (Ph) chromosome with BCR-ABL fusion gene." (PMID 38164178, 2024). "Compared to chemotherapy, it often has fewer side effects and a better quality of life for patients, more examples, such as imatinib (Gleevec), which is used in treating chronic myeloid leukemia (CML), targets the BCR-ABL tyrosine kinase, which is active in CML cells." (PMID 39328627, 2024). "Negative BCR-ABL fusion gene testing ruled out Philadelphia chromosome-positive chronic myeloid leukemia." (PMID 39395952, 2024). "Chronic Myeloid Leukemia (CML) is characterized by the presence of a translocation between chromosomes 9 and 22 in the hematopoietic stem cell, leading to the expression of the chimeric protein BCR-ABL." (PMID 39199564, 2024). "There is still a lack of reliable molecular predictors to achieve major molecular response (MMR, BCR::ABL1 ≤ 0.1% IS) within the first year of treatment with tyrosine kinase inhibitors (TKI) in the therapeutic management of newly diagnosed chronic myeloid leukemia (CML)." (PMID 37174118, 2023). "Dasatinib, a targeted inhibitor of oncogenic breakpoint cluster region-Abelson leukemia virus (BCR-ABL) tyrosine kinase, has profoundly improved the outcome of chronic myeloid leukemia (CML) and Philadelphia-chromosome-positive acute lymphoblastic leukemia (Ph-ALL)." (PMID 36691104, 2023). "Chronic myeloid leukemia (CML) is characterized by the Philadelphia (Ph) chromosome, an acquired clonal abnormality resulting from the translocation of chromosomes and the generation of BCR-ABL fusion oncogenes." (PMID 35815090, 2022). "Chronic myeloid leukemia (CML) is a myeloproliferative neoplasm derived from the balanced reciprocal translocation of chromosomes 9 and 22 t (9q34 and 22q11), which leads to the formation of the Philadelphia chromosome and fusion of the BCR-ABL genes." (PMID 35205374, 2022). "Chronic Myeloid Leukemia (CML) is a hematopoietic stem cell malignancy characterized by the acquisition of the t chromosomal translocation leading to expression of the BCR/ABL oncogene." (PMID 36304465, 2022). "Atypical chronic myelogenous leukemia (aCML), BCR/ABL1 negative is a rare myelodysplastic/myeloproliferative neoplasm, usually manifested with hyperleukocytosis without monocytosis or basophilia, organomegaly, and marked dysgranulopoiesis." (PMID 34868917, 2021).